CTSK (cathepsin K)
Diseases named in the same sentence as CTSK in open-access papers (continued):
Sharing a sentence is not in itself a finding about the gene and the disease.
tumor (continued). "In multivariate analysis, CTSK protein expression (tumor), corrected for pathological T stage, remained a strong prognostic factor for regional disease, demonstrating an odds ratio of 9 (CI: 2.83–31.65; p < 0.01)." (PMID 29618339, 2018). "The majority of the OSCCs in this cohort showed a weak expression for CTSK (42% in tumor cells and 54% in stromal cells), whereas only 5% demonstrated no expression in tumor cells." (PMID 29618339, 2018). "The only significant finding was that CTSK expression in stromal cells exhibited a potential protective role, since a poorer prognosis in early stage tumors was correlated to weak CTSK expression in the tumor microenvironment front." (PMID 29618339, 2018). "Genes associated with tumor invasiveness and epithelial to mesenchymal transition (EMT); CTSK and PLAC8 respectively, were also identified as being upregulated in CL tumors." (PMID 28045912, 2017). "Tumor expansion was monitored by the luciferase activity of ARCaPM-Luc cells, while osteoclast activity was visualized by osteoclast-cathepsin K activity." (PMID 29152128, 2017). "While the majority of cells in human renal AMLs typically stain strongly and diffusely for CATHEPSIN K27, our allograft tumours exhibited a weak diffuse cytoplasmic positivity with ~10% of cells exhibiting strong immunoreactivity for CATHEPSIN K." (PMID 29133867, 2017). "The tumor-promoting functions of cathepsin K have been mainly discussed in the context of bone metastasis." (PMID 26157794, 2015). "Since the tumor environment is inherently acidic due to high rate of glycolysis (Warburg Effect) the necessary trigger for secreted CTSK to act on latent proMMP-9 is ever present." (PMID 26219353, 2015). "Blocking cathepsin G and cathepsin K significantly reduces tumor-induced osteolysis, which suggests that cathepsin K and cathepsin G are crucial in the microenvironment of cancer-induced osteolytic lesions." (PMID 26440411, 2015). "Apart from its well-confirmed involvement in metastatic bone disease, cathepsin K seems to have a more general role in tumor progression." (PMID 26157794, 2015). "Cathepsin K found in the tumor-bone interface is responsible for the production of NTx, a marker of bone turnover, which is generated from the degradation of bone matrix collagen I." (PMID 26440411, 2015). "In lymph node metastases, the pattern of cathepsin K expression was similar to the one found in the corresponding primary tumors, indicating that invasive tumor cells quickly mobilize the host stromal cells and modify their new surroundings." (PMID 23951042, 2013). "In certain tumours, macrophages positive for NS-related genes, such as cathepsin K, were evenly scattered throughout the tissue, whereas in other samples they clustered around ECM deposits." (PMID 19773754, 2009). "Additionally, gut dysbiosis, driven by E. coli, elevates LPS levels, triggering tumor-secreted cathepsin K (CTSK)." (PMID 41355895, 2025). "Moreover, elevated LPS result from gut microbiota imbalance has been implicated in the secretion of cathepsin K (CTSK), which further promotes CRC metastasis by stimulating M2 polarization of tumor-associated macrophages (TAMs) through the TLR4/mTOR pathway." (PMID 40181829, 2025). "Digital pathology combined with AI-assisted image analysis was employed to quantify and visualize the spatial distribution of OSCC cells (RANKL-positive), CAFs (α-SMA and FAP-positive), and osteoclasts (cathepsin K-positive) within defined regions of interest at the tumor–bone invasive front." (PMID 41153834, 2025). "Additionally, we observed upregulation of CTSK, which is mainly expressed by osteoclasts that participate in bone matrix resorption and contribute to tumor invasiveness." (PMID 40596459, 2025). "IHC with Cathepsin K confirmed presence of osteoclasts in the tumour centre versus the periphery." (PMID 41315643, 2025).
tumor (continued). "Furthermore, cathepsin K affects the polarization of M2 macrophages in CRPC and regulates tumor progression and metastasis through the IL-17/CTSK/EMT signaling pathway." (PMID 40556678, 2025). "Notably, tumor-derived secretory proteins such as cathepsin K (CTSK) can activate tumor cell migration via autocrine signaling and induce macrophage M2 polarization by binding to TLR4 receptors and stimulating mTOR-dependent pathways." (PMID 41353343, 2025). "Furthermore, CTSK plays an important regulatory role in tumour invasion and metastasis by degrading the collagen matrix." (PMID 38594611, 2024). "CTSK activates macrophages to secrete IL-4, IL-10, and IL-17, promoting tumor growth and invasion." (PMID 39736788, 2024). "In addition to osteoclasts, cathepsin K expressed by tumor and other cells within the tumor microenvironment can promote bone metastasis." (PMID 39148909, 2024). "In vivo, the tumor secreted secretory protein cathepsin K which could stimulate the M2 polarization and thereby facilitate the progression of CRC." (PMID 38270646, 2024). "This expression pattern suggests that while Cathepsin K is present in both types of tumours, the differences in staining intensity might serve as a definitive marker for differentiating between the two." (PMID 39684226, 2024). "It is hypothesized that the TFE3 fusion proteins function like MITF in the neoplasms, and thus activate cathepsin K expression which can be detected by IHC." (PMID 37218666, 2024). "Altogether, our analysis provided lines of evidence to support the hypothesis that macrophages may express MMP9 and CTSK in order to help tumor cell growth and break through the seminiferous tubules." (PMID 38123589, 2023). "There were statistically significant differences in CTSK immunoexpression concerning the following different variables; tumor type, tumor histologic grade, tumor size, the status of nodal involvement, metastasis, TNM clinical stage, and the incidence of recurrence (p < 0.05)." (PMID 37198626, 2023). "Many pathways may be triggered in the mechanism by which CTSK could promote the proliferation, invasion, and migration of tumor cells (RANK/RANKL, TGF-B, mTOR, and Wnt/β-catenin pathways)." (PMID 37198626, 2023). "More recently, using a Cd200 conditional null mouse model, we identified the collagen peptidase Cathepsin K (Ctsk) as a crucial target gene of the Cd200-Cd200r signaling axis in Cd200r+ tumor-infiltrating myeloid lineages, which was required for tumor cell invasion and metastasis." (PMID 36738455, 2023). "Separate administering specific inhibitors of mammalian target of rapamycin (mTOR) and NF-κB pathways, such as rapamycin and BAY11–7082, to block each key nodal pathway showed that tumor-secreted CTSK combined with TLR4 via the mTOR-dependent pathway stimulates TAMs to polarize toward M2 phenotype." (PMID 37943609, 2023). "We hypothesized that CTSK was involved in angiogenesis and stromal remodeling in tumor tissue, and similarly, NRP1 induced epithelial-mesenchymal transition (EMT) by promoting GC metastasis via activating PI3K/Akt signaling pathway." (PMID 37930479, 2023). "Moreover, they also observed a correlation between the diminished CTSK expression in the tumor microenvironment (TME) and the increased overall recurrence." (PMID 37198626, 2023). "Also, CTSK inhibition reduces the progression of osteolytic lesions, indicating the significance of CTSK as a tumor biomarker." (PMID 37198626, 2023). "By co-staining of MMP9 and CTSK, and K8, we found that MMP9 level was elevated in CTSK-positive cells at the tumor-bone boundary of the miR-182-OE lesions compared with the control group, further confirming the increase of osteoclastogenesis at the tumor-bone boundary." (PMID 37127752, 2023). "And GSEA was used to investigate the potential role of CTSK in the tumor microenvironment of GC." (PMID 37930479, 2023). "CD44 can promote tumor metastasis, and then, CTSK and MMP-9 were detected, and both were positive." (PMID 36005209, 2022).
tumor (continued). "The control + IL-17A group and the CTSK siRNA + IL-17A group showed higher expression of CTSK compared to the other two groups; therefore, we conducted flow cytometry on the tumor tissues of the four groups of nude mice to observe the immune cells infiltration." (PMID 36138018, 2022). "However, a higher expression of CTSK was seen in localized PC with the higher accumulation of M2 TAMs in stroma of the tumor." (PMID 36138018, 2022). "A positive correlation was observed between CTSK expression and tumor size (r=0.671, p<0.001)." (PMID 36052250, 2022). "There are three main effects of CTSK inhibitors: inhibition of PCa cell invasiveness, dose-dependent inhibition of PCa-conditioned mediator-induced bone resorption and the effective prevention of tumor formation." (PMID 36005209, 2022). "Second, IL-17A could increase the expression of CTSK in PC cells and in tumor tissues of mice, and promote EMT marker expression through CTSK in PC cells." (PMID 36138018, 2022). "Moreover, CTSK promoted tumor growth in vivo and enhanced the ability of metastasis and invasiveness in vitro, showing its important function in tumor microenvironment and in improving the progress of PC." (PMID 36138018, 2022). "Furthermore, it has been demonstrated that gut microbiota such as Escherichia coli stimulates metastasis-related secretory protein cathepsin K, which is a crucial mediator between dysbiosis and tumor burden." (PMID 35892821, 2022). "Moreover, MMP-9 can be cleaved and activated by CTSK in acidic environments, such as tumor and bone resorption." (PMID 36005209, 2022). "CTSK can degrade the extracellular matrix (ECM) to promote the invasion and metastasis of various human cancer types; therefore, the levels of CTSK might be an effective index for assessing the tumor severity or predicting the prognosis of cancers." (PMID 36005209, 2022). "Similarly, EO771 tumor cell-derived CM increased the number of TRAP-positive RAW264.7 osteoclasts with elevated levels of cathepsin K and NFATc1 in 5 days." (PMID 34830748, 2021). "In the gastric metastasis model, the use of the pharmaceutical agent Odanacatib significantly inhibited the metastases of cancer cells, suggesting that Cathepsin K inhibition may be employed as a new therapeutic strategy to prevent tumor metastasis." (PMID 32927648, 2020). "Furthermore, bone marrow macrophages (BMMs) are the major source of cathepsin K (CTSK), which promotes tumor progression in bones." (PMID 33262947, 2020). "Cathepsin K contributed to tumor macrophage recruitment via increased levels of chemokine CCL2." (PMID 31555270, 2019). "Furthermore, immunofluorescent staining showed decreased expression of Cathepsin-K, a key protease for bone destruction, at the tumor-bone interface in the RiCKO mice compared with the control mice." (PMID 31595162, 2019). "Third, the findings of the previous study were solely based on immunohistochemistry and were, partly, contradictory with the observation, reported by the same authors, of the diminished invasion potential of the HSC-3 tumor cells, when cathepsin K was silenced or inhibited." (PMID 29618339, 2018). "However, the same study found decreased invasion of HSC-3 tumor cells when cathepsin K silencing was applied." (PMID 29618339, 2018). "It was, thus, concluded that different prognosis could be exhibited, depending on whether CTSK is expressed more in tumor or stromal cells." (PMID 29618339, 2018). "In logistic regression analysis, factors with known impact to nodal disease were incorporated into the model, including T stage, perineural and vaso-invasion, depth of infiltration and spidery growth pattern, along with CTSK protein expression in tumor and in stroma cells." (PMID 29618339, 2018). "Finally, the emergence of new CTSK inhibitors, like odanacatib, can provide in the future a new tool for the suppression of tumor progression in patients with inoperable disease." (PMID 29618339, 2018).
tumor (continued). "In human breast cancer, Cathepsin-K contributes to tumor spread." (PMID 28634389, 2017). "Finally, cathepsin K produced by tumour cells has been shown to promote tumour cell invasiveness and contribute to bone degradation." (PMID 27782035, 2016). "However, the ability CTSK-proMMP-9 nexus to influence and alter tumor behavior needs to be verified in vivo." (PMID 26219353, 2015). "In some samples, we observed a gradient of staining intensity accompanying the variations in expression of cathepsin K. This seems to be an epithelial-to-mesenchymal pattern shift in the expression of cathepsin K as the tumor begins to reach more invasive areas of the tumoral tissue." (PMID 23951042, 2013). "Acidic tumour environment due to the increasing rate of glycolysis, however, might trigger the secretion of Cathepsin K as a member of lysosomal cysteine cathepsin (LCC) subgroup, which competed to disrupt cysteine interaction with zinc in proMMP-9, resulting in active MMP-9 production." (PMID 37600570, 2023). "Interestingly, the inhibition of CTSK could be able to reduce the progression of osteolytic lesions, suggesting that CTSK may have greater significance as a tumor biomarker." (PMID 36005209, 2022). "Therefore, CTSK inhibitors may be considered as a potential therapeutic targets to reduced tumor metastasis." (PMID 36138018, 2022). "In addition, CTSK can promote tumor cells proliferation, invasion and migration, and its mechanism may be related to RANK/RANKL, TGF-β, mTOR and the Wnt/β-catenin signaling pathway." (PMID 36005209, 2022). "Using CIBERSORT algorithm, we analyzed the ratio of immune-cell subsets in tumor infiltration, and established 22 types of profiles of immune cells from PC samples (276 tumor samples with p < 0.05) to demonstrate the relationship of immune microenvironment with IL-17A/CTSK." (PMID 36138018, 2022). "Moreover, bone matrix degradation by cathepsin K may facilitate the tumor growth of osseous metastasis." (PMID 34069976, 2021). "Moreover, tumor-secreted cathepsin K (CTSK) could stimulate TLR4 to switch to M2 polarization relying on the mTOR signaling activation." (PMID 33505964, 2020). "Survival analysis demonstrated CTSK protein expression in both stromal and tumor cells as significant indicators of poor 5-year disease specific survival (HR = 2.40, CI:1.05–5.50, p = 0.038 for stromal cells; HR = 2.79, CI:1.02–7.64, p = 0.045 for tumor cells)." (PMID 29618339, 2018). "Moreover, cathepsin K expression was noted in only 31% of the cases of esophageal invasive squamous cell carcinoma (being particularly confined to the relatively sparse cancer cells located externally in the tumor foci)." (PMID 23833636, 2013). "Moreover, cathepsin K expression in BSCC may contribute to tumor invasion and its highly aggressive clinical course since this protein has marked collagenolytic and elastolytic activities." (PMID 23833636, 2013). "The enhanced tumor accumulation following PGA-Dtx administration significantly suppressed tumor growth in vivo, normalized cathepsin K activity levels, and reduced bone damage while avoiding the systemic toxicity associated with free Dtx." (PMID 41608564, 2026). "Canonical markers were used to annotate different cell types: malignant cells (COL1A1, IBSP), myeloid cells (CD74, CD14), osteoclasts (CTSK, MMP9), pericytes (RGS5, ACTA2), endothelial cells (PECAM1, VWF), and tumor-infiltrating lymphocytes (CD3D, NKG7)." (PMID 40730548, 2025). "Parietal peritoneal thickening showed the overexpression of LUM, MMP11, and DUSP1 in the tumor region, MMP11 and CTSK in the stromal region, and MMP11 and CTSK in the immune region (adjusted p-values ≤ 0.002)." (PMID 39135097, 2024). "Secondly, there was a lack of corresponding experimental evidence to demonstrate that CTSK functioned in angiogenesis and ECM remodeling in tumor development." (PMID 37930479, 2023).
tumor (continued). "The current findings supported a critical role of CTSK in tumor development and explored the relationship between CTSK and TME of GC, immune checkpoints and tumor-infiltrating immune cells." (PMID 37930479, 2023). "Cathepsin K (CTSK), a protease that degrades type I collagen and ECM, thereby contributing to bone resorption and tumor invasion, has been reported as a potential marker for sphenoid sinus and clivus invasion." (PMID 37958702, 2023). "To further validate, we performed Immunofluorescence (IF) staining for MMP9 and CTSK in the tumor patient tissues and found that both MMP9 and CTSK had a co-localization with CD68." (PMID 38123589, 2023). "Taken together we can infer that the evidence of interaction between tumor-infiltrating immune cells and CTSK in TME supported the potential of CTSK as a novel GC immunotherapeutic target." (PMID 37930479, 2023). "Cathepsin K mediates M2 macrophage polarization through a TLR4-dependent pathway and supports tumor metastasis in CRC." (PMID 35892821, 2022). "In summary, IL-17A induced CTSK expression to disrupt E-cadherin/β-catenin complex, released β-catenin, and enhanced EMT and tumor cell invasion." (PMID 36138018, 2022). "Gut microbiota-stimulated cathepsin K secretion mediates TLR4-dependent M2 macrophage polarization and promotes tumor metastasis in colorectal cancer." (PMID 35110624, 2022). "A heatmap profiles showed that CTSK, MMP9, CKB, CCL18 and COL6A2 were upregulated in macrophages in tumor tissues." (PMID 36466840, 2022). "Spots with averaged expression of CTSK and PMEL higher than 50% across all spots were annotated as tumor spots(yellow)." (PMID 36028490, 2022). "We assessed the expression levels of candidate invasion-specific protein biomarkers CTSK, MMP9, MMP2, TIMP2, and PTTG1 by immunohistochemical staining in paraffin-embedded NFPA tumor tissues." (PMID 36052250, 2022). "Gut microbiota imbalance in colorectal cancer, stimulates CTSK secretion which, in turn, mediates the TLR4-dependent M2 polarization of TAMs to promote tumor metastasis in a positive feedback loop." (PMID 33809973, 2021). "In immunohistochemical analyses, tumor cells exhibit diffuse nuclear labeling for TFE3 protein and cytoplasmic reactivity with Cathepsin K and HMB45." (PMID 30103811, 2018). "These tumours showed similar patterns of immunoreactivityto tumours obtained from whole sphere populations when stained with antibodies against PMEL, SMA, PDGFRβ, CATHEPSIN K, NG2 and S100, as well as displayed E-CADHERIN positive epithelial structures." (PMID 29133867, 2017). "Allograft tumours from SC2 and SC4 express melanocyte genes and the proteins PMEL, MiTF and CATHEPSIN K." (PMID 29133867, 2017). "IL–20 induced the expression of N-cadherin, STAT3, vimentin, fibronectin, RANKL, cathepsin G, and cathepsin K, all of which are involved in cancer cell migration, EMT, and tumor-induced osteolysis." (PMID 26440411, 2015). "We showed here, for the first time, that cathepsin K is abundantly expressed by OTSCC cells in addition to the tumor microenvironment (TME), and that its expression pattern by tumor cells has prognostic significance." (PMID 23951042, 2013). "Not only that, the organization of the stroma seemed to mimic the one found at the primary tumor, with inflammatory cells organized around OTSCC cells and expressing increased amounts of cathepsin K." (PMID 23951042, 2013). "We used the Human Tumor Metastasis PCR Array to confirm that two proteases (MMP-9 and cathepsin K) were responsible for coronin 3-related metastasis." (PMID 22974233, 2012). "Moreover, CTSK activates pre-MMP-9 to generate MMP-9 under acidic conditions, promoting tumour cell migration and metastasis." (PMID 38594611, 2024). "These tumours are positive for CK7, CD117, Cathepsin K, and SDHB." (PMID 38265103, 2024).